UBE2C (ubiquitin conjugating enzyme E2 C)
Diseases named in the same sentence as UBE2C in open-access papers (continued):
Sharing a sentence is not in itself a finding about the gene and the disease.
tumor (continued). "In order to further determine the relationship between UBE2C and the tumor microenvironment (TME), we also examined the correlation between UBE2C and immune checkpoint-related genes by analysis of The Cancer Genome Atlas (TCGA) data." (PMID 34858987, 2021). "Then we can find there are 65 “good genes” among them, and most of 65 “good genes” are negatively correlate with tumor stage, while the only 4 “bad genes” (CDC20, CDCA3, FBXL6, UBE2C) are positively correlate with tumor stage." (PMID 34093816, 2021). "For each patient sample block, two tumor tissue spots and one normal control spot were used for TMA; IHC analysis of UBE2C is shown as an example." (PMID 33396624, 2020). "As for the protein expression level's validation, it was assessed to indicate that UBE2C and TPX2 expressions were significantly higher in tumor tissues than in normal tissues in accordance with the Human Protein Atlas database." (PMID 32309427, 2020). "This study shows that FOXM1 and UBE2C are overexpressed and positively correlated in ESCC as well as in a wide range of distinct tumor types." (PMID 29596365, 2018). "Consistent with a proposed switch in the AR driven transcriptional program with local tumour progression, we observed a consistent increase in the expression of a number of these genes in higher-grade tumours, particularly CDK1, UBE2C, CDC20 and CCNA2." (PMID 27120785, 2016). "The positive rates of UBE2C and MGP in ESCC tumor tissues were up to 43.4% (89/205) and 41.5% (85/205), respectively." (PMID 27556859, 2016). "Even for the therapy-naïve study cohort, differential gene expression was a significant prognosticator within tumor sets defined by their WHO grades (WHO°I: AURKB, COX10, ECT2, UBE2C; WHO°II: LEPR, MN1; WHO°III: PTTG1, UBE2C)." (PMID 26894859, 2016). "To evaluate the potential use of UBE2C and MGP as biomarkers for ESCC, we analyzed the protein levels of UBE2C and MGP in 205 training ESCC tumor tissues by immunohistochemistry (IHC)." (PMID 27556859, 2016). "The positive rates of UBE2C and MGP in ESCC tumor tissues were up to 56.5% (117/207) and 53.6% (111/207), respectively." (PMID 27556859, 2016). "The survival prediction model consisting of two genes (UBE2C and MGP) and two clinicopathological factors (tumor stage and grade) was developed." (PMID 27556859, 2016). "According to a previous review, we measured the mRNA expression of 5 tumor initiation genes and 20 metastasis initiation, progression and virulence genes in MCF-7 cells with UBE2C knockdown." (PMID 24699941, 2014). "The levels of the tumor initiators HER2 and KRAS and metastasis genes VEGF, CXCL-4, CCL5, NEDD9 and RHoC were reduced in MCF-7 cells with UBE2C knockdown and increased with UBE2C overexpression." (PMID 24699941, 2014). "Concurrently, tumor tissue and primary cultures displayed low transcript levels of proliferation-related genes, such as, TOP2A, ANKT, RAD51, UBE2C, CENPA, RRM2, and PLK." (PMID 15260889, 2004). "Analysis of B- and plasma cells (26,156 cells) showed that germinal centre (GC) B-cells (RGS13+, NEIL1+), cycling B-cells (UBE2C+, TYMS+) and naïve B-cells (TCL1A+, IL4R+) were all enriched in HPV+ve tumours compared to HPV-ve tumours, while switched B-cell subsets were found in both." (PMID 39757146, 2025). "The qRT-PCR results revealed pronounced upregulation of TFF1, ITPKA, UBE2C, and IGFBP3, along with marked downregulation of SLC34A2 and SELENBP1 in tumor samples relative to adjacent normal tissues, which was in strong agreement with the transcriptomic profiling outcomes." (PMID 40787454, 2025).
tumor (continued). "In the multivariate analysis, after adjusting for UBE2C, AGGF1, microvessel density (MVD), tumor size, LNM, and TNM stage, positive VM status remained an independent predictor of mortality, increasing the risk by 2.1-fold (multivariate HR 2.107, 95% CI: 1.226–3.622, p=0.007)." (PMID 40786517, 2025). "Furthermore, experimental data confirmed that UBE2C overexpression promotes HCC cell proliferation, invasion, and metastasis, further supporting its role in tumor progression and TME remodeling." (PMID 40290433, 2025). "UBE2C was found to be overexpressed in various of tumors, including LUAD, and its expression level was found to be significantly related to gender, weight, tumor stage, grade and prognosis in LUAD." (PMID 38370368, 2024). "Other studies have described that UBE2C, along with the other signaling molecules such as AURKA, EMT, GRIK3, CDK1, and claudin 19, activates the WNT/β-catenin signaling pathway, thus altering tumor biology." (PMID 39479352, 2024). "After cellular annotation of the 6 tumour cell types based on marker gene expression, we were able to identify the following: C0 PSCA+ tumour cells, C1 CLDN7+ tumour cells, C2 UBE2C+ tumour cells, C3 MUC6+ tumour cells, C4 CHGA+ tumour cells and C5 MUC2+ tumour cells." (PMID 38894657, 2024). "Consistent with our in vitro findings, A549-bearing mice treated with IT3 siRNAs exhibited a rapid tumor growth curve and shortened survival time compared to the scramble group, indicating that the SLIT3/UBE2C/Wnt axis promotes NSCLC progression and chemoresistance." (PMID 39479352, 2024). "However, if exogenous human SPP1 protein is added, the expression of proliferation‐related genes (UBE2C, E2F1) in the co‐cultured tumor cells increases." (PMID 39716897, 2024). "Concordant with their roles in tumor progression, the TREM2+ and UBE2C+ TAMs were abundant in PTs compared to NTs and MTs, which was concordant with their prognostic values for predicting poor survival of patients with primary liver tumors rather than metastatic liver tumors." (PMID 38414027, 2024). "Hence, explaining the relationship between UBE2C and m6A regulators in ACC can enhance our understanding of the mechanism of UBE2C promoting the tumor development." (PMID 37535572, 2023). "We found that KO in the lung of Ube2c, but not Ube2s, substantially reduced the tumor burden and prolonged mouse lifespan, indicating that Ube2c is a Kras-cooperative gene, largely required for Kras-induced lung tumorigenesis." (PMID 36548081, 2023). "Notably, we found substantial connections between the expression of BIRC5, E2F1, SFN, and UBE2C and the pathological stage of HCC, indicating their potential as indicators of tumor progression and severity." (PMID 38283837, 2023). "UBE2C mRNA level was validated in normal and UCEC tumor samples applying the UALCAN web tool." (PMID 37803076, 2023). "This suggests that the combined inhibition of UBE2C and PLK1 may more significantly suppress tumor progression by inducing cell cycle arrest and apoptosis than either of them alone." (PMID 37958642, 2023). "In consideration of the UBE2C overexpression in HNSCC and its critical role in tumor progression, we hypothesized that UBE2C could regulate the radiotherapy sensitivity of human HNSCC." (PMID 36069832, 2022). "Our result initially indicated that UBE2C knockdown might promote the EMT process in THCA, which plays a key role in the process of tumor invasion and metastasis." (PMID 35332135, 2022). "Notably, UBE2C, which acts as one of the critical biomarkers specifically expressed in CD8+ T_3 cells, is involved in tumor progression and has essential prognostic value." (PMID 35812372, 2022). "Ubiquitin-conjugating enzyme E2C (UBE2C), a crucial member of the E2 family, is involved in the cell cycle process through interacting with the late-promoting complex/annular port (APC/C) and identified as a novel potential tumor biomarker." (PMID 34950739, 2021).
tumor (continued). "Ten of 12 transcripts that were prognostic in Gleason score 7 tumours remained prognostic in patients with Gleason 3 + 4 = 7 tumours, and multivariable logistic regression analysis showed that combining CCNB1 or UBE2C with SRD5A2 slightly improved the predictive power of the model." (PMID 30616540, 2019). "In conclusion, this study provides evidences that FOXM1 transcriptionally regulates UBE2C expression in ESCC and their deregulation may be a general phenomenon in human neoplasias." (PMID 29596365, 2018). "Additionally, we evaluated the distribution of UBE2C mRNA expression levels in the groups of healthy esophageal tissues, ESCC samples and tumor surrounding mucosa, being the mRNA levels median values of 0.0011; 0.0019 and 0.0039, respectively." (PMID 27588470, 2016). "UBE2C, CCNB1, CCNB2, PLOD2, NUP210, MELK, CDC20 were overexpressed in tumours and in CIN3/CIS relative to both Normal and CIN1/CIN2, suggesting that they could have an important role to play in the early phase of tumorigenesis." (PMID 21338529, 2011). "Several genes located on 20q, for example, the oncogenes located on 20q13.1, such as CAS/CSE1L, NABC1, ZNF217, Aurora2 (BTAK, STK15) and the ubiquitin-conjugating enzyme E2C (UBE2C), have been described to have an important role in tumour progression and liver metastases." (PMID 21673680, 2011). "UBE2C, CCNB1, CCNB2, PLOD2, NUP210, MELK, CDC20 genes were overexpressed in tumours and in CIN3/CIS relative to both Normal and CIN1/CIN2, suggesting that they could have a role to play in the early phase of tumorigenesis." (PMID 21338529, 2011). "Since we found that knockdown of UBE2C reduced the expression of TOP2A, we speculated that inhibiting UBE2C might have a synergistic effect with doxorubicin, enhancing its ability to inhibit TOP2A expression and reach a better anti‐tumor effect." (PMID 40729680, 2025). "Hence, we speculate that the overexpression of UBE2C inhibits the invasion of B cells and CD4+ T cells, thus accelerating tumor progression in LUAD." (PMID 38370368, 2024). "After that, we re-subtypeed tumor cells, and annotated them according to each cell marker gene, and identified six tumor cell subtypes: C0 XIST+ tumor cells, C1 SCGB2A1+ tumor cells, C2 IGF2+ tumor cells, C3 UBE2C+ tumor cells, C4 TFF3+ tumor cells and C5 IGFBP3+ tumor cells." (PMID 39896800, 2024). "Subsequent PPI and survival analysis results demonstrated that UBE2C may be a key downstream gene involved in the ALKBH5 promoting function in the TNBC cell stemness and tumor progression where ALKBH5 regulated the m6A modification of UBE2C and consequently upregulated UBE2C expression." (PMID 36551544, 2022). "Furthermore, TPX2, ZWINT, UBE2C, CCNB2, CDK1, BUB1, and BIRC5 may orchestrate the stemness, proliferation, and invasion of tumor cells." (PMID 34671679, 2021). "Upon UBE2C silencing there was a decrease in cell proliferation of EAC and ESCC cell lines, whereas RNF113A knockdown resulted in reduced proliferation and increased apoptosis, as well as inhibition of the migratory and invasive capacities of ESCC cell lines and decreased tumour growth in nude mice." (PMID 32429269, 2020). "Further, the levels of UBE2C expression detected in ESCC group were significantly higher than those found in the other groups, being its median expression value approximately 3.5- and 2.0-fold higher than those found in healthy and tumor surrounding esophageal tissue groups, respectively." (PMID 27588470, 2016). "However, we found a significant accumulation of DEPTOR, a tumor suppressor and a naturally occurring inhibitor of mTORC1/2, implying that the DEPTOR/mTORC pathway could be involved in the growth-suppressing effect of UBE2C knockdown." (PMID 36548081, 2023).
tumor (continued). "Hence, we concluded that UBE2C may be a critical factor for predicting the prognosis of ccRCC patients and that the detected expression level of UBE2C from PBMC may contribute to predicting tumor progression and aid immunotherapy in ccRCC." (PMID 35812372, 2022). "High expression of UBE2C was significantly associated with the presence of LVI (p = 0.009), and other variables of poor prognosis including the presence of nodal status, high tumour grading, larger tumour size, poor NPI, lack of ER and PR receptors expression, and HER2 positivity." (PMID 35124721, 2022). "Importantly, the differential expression of UBE2S and UBE2C across histologic subtypes were further corroborated in bulk transcriptome from the TCGA and the East Asian ancestry (EAS) cohorts, as well as proteome from the Clinical Proteomic Tumor Analysis Consortium (CPTAC) cohort." (PMID 36138435, 2022). "Multivariate analysis in METABRIC cohort observed that UBE2C expression was an independent prognostic marker significantly associated with poor patient outcome in terms of BCSS (p < 0.001, HR 1.90, 95% CI; 1.50–2.38), regardless of LVI, tumour size, ER and HER2 status." (PMID 35124721, 2022). "However, single-factor detection of UBE2C might be not sufficient to identify the tumor type or tumor progression in core biopsy specimens." (PMID 24699941, 2014). "Strikingly, we noticed that the expression of UBE2C in CD8+ T_3 cluster cells is almost identical, regardless of origin (tumor tissue, adjacent normal tissue, or PBMC in ccRCC)." (PMID 35812372, 2022). "Subsequently, immunohistochemical analysis confirmed that UBE2C protein expression was upregulated in all ESCC cases, but absent in the histologically normal tumor surrounding tissues." (PMID 27588470, 2016). "Furthermore, in tumor tissues from NSCLC patients, we identified a notable negative correlation between SLIT3 expression and UBE2C levels." (PMID 39479352, 2024). "The relative expression levels of CDKN3, MKI67, CEP55, SPAG5, AURKA, TOP2A were consistent with the results of bioinformatics analysis (P < 0.05), while the expression levels of UBE2C, CHEK1 and BIRC5 in tumor samples were not significantly different from adjacent normal samples." (PMID 35178291, 2022). "We found that the expression levels of UBE2C, CHEK1, and BIRC5 in tumor samples were not significantly different from adjacent normal samples, which may be due to the small sample size." (PMID 35178291, 2022). "Furthermore, immunohistochemical analysis of UBE2C protein corroborated the gene expression data, once UBE2C protein was quite abundant in most of the ESCC samples, whereas it was completely absent in tumor surroundingtissues." (PMID 27588470, 2016). "In order to analyze the profile of UBE2C mRNA expression in tumor and non-tumor esophageal tissue, we evaluated its expression in 52 ESCC paired samples (tumor and histologically normal surrounding tissue) and 5 samples of normal esophageal tissue from healthy subjects by qRT-PCR." (PMID 27588470, 2016). "Furthermore, UBE2C (ubiquitin-conjugating enzyme E2C) mRNA was overexpressed in EAC compared to Barrett’s metaplasia (although the authors did not quantify this difference) and protein immunostaining was observed in tumour tissue, whereas Barrett’s metaplasia samples were negative." (PMID 32429269, 2020).
adenocarcinoma (5 papers, 2010 to 2023). A common cancer characterized by the presence of malignant glandular cells. "Because gene expression at the mRNA level does not always correspond to protein levels, we then examined the expression of the protein products of Ube2c, Fen1 and Mcm2 in Gprc5a−/− lung normal and adenocarcinoma tissue and cells." (PMID 20686609, 2010). "A key feature of the signature, up-regulation of Ube2c, Mcm2, and Fen1, was validated in mouse normal lung and adenocarcinoma tissues and cells by immunohistochemistry and western blotting, respectively." (PMID 20686609, 2010). "Using comparative functional genomics and functional pathways analysis followed by validation at the protein level by immunohistochemistry and western blotting analyses, we highlighted the marked up-regulation of Ube2c, Mcm2 and Fen1 in Gprc5a-knockout mouse adenocarcinoma relative to normal lung." (PMID 20686609, 2010). "In accordance, Mcm2, Fen1, Ube2c and cyclin D1 proteins were also relatively higher in the MDA-F471 mouse adenocarcinoma cells compared to the normal Gprc5a−/− cells as revealed by the western blotting analysis." (PMID 20686609, 2010).
infection (5 papers, 2013 to 2023). The state of being infected such as from the introduction of a foreign agent such as serum, vaccine, antigenic substance or organism. "After 24 h of infection, the expression levels of UBE2C and PSMD6 the expression levels returned to unstimulated baseline levels, while SUMO1, SUMO2 and PSMC1 showed slightly higher expression levels than uninfected control cells." (PMID 37165081, 2023). "Of the top 10 transcripts upregulated at peak HIV-1 viral load, the majority (6 out of 10) were related to cell cycle and cell division including RRM2, MYBL2, CDK1, UBE2C, CDC45, and TK1 with 8 to 15-fold increased expression compared to the pre-infection samples." (PMID 31937782, 2020). "Thus, the possible relationship between the infection of EBV and up-regulation of UBE2C in NPC should deserver much attention." (PMID 23587173, 2013).
urological diseases (1 paper, 2025). "CD24, TOP2A, IQGAP3, UBE2C, and CRH mRNA levels were also significantly higher in patients with NMIBC than in those with hematuria, which may indicate that they could be used as discriminative biomarkers for BCa detection compared to urological diseases." (PMID 40282460, 2025).
UBE2C also shares sentences with these, for which no sentence is quoted: multiple myeloma (4 papers); astrocytic tumor (3); Pan (3); astrocytomas (2); breast (2); Hashimoto thyroiditis (2); hematologic disorder (2); invasive breast carcinoma (2); large cell lung cancer (2); lymphoid neoplasm (2); metastatic tumor (2); myocarditis (2); nodular goiter (2); pancreatic ductal adenocarcinoma (2); prostate adenocarcinoma (2); prostate neoplasm (2); thyroid (2); acute lymphoblastic leukemia (1); adenoma (1); adrenal cancer (1); allergic asthma (1); anaplastic carcinoma (1); Barrett's metaplasia (1); bladder urothelial carcinomas (1); bone osteosarcoma (1); brain glioma (1); breast adenocarcinoma (1); Carcinoid (1); digestive system tumors (1); ductal carcinoma (1).
A further 33 diseases each share a sentence with UBE2C in 1 paper.